MAIP1 (matrix AAA peptidase interacting protein 1)
Description:
Promotes sorting of SMDT1/EMRE in mitochondria by ensuring its maturation. Interacts with the transit peptide region of SMDT1/EMRE precursor protein in the mitochondrial matrix, leading to protect it against protein degradation by YME1L1, thereby ensuring SMDT1/EMRE maturation by the mitochondrial processing peptidase (PMPCA and PMPCB).
Synonyms: C2orf47; DKFZp666A212; FLJ22555
Tractability: PROTAC: ubiquitination databases record sites on it.
Gene: Protein-coding gene on chromosome 2 (199,955,317 to 200,008,540, forward strand). Ensembl gene ENSG00000162972.
Subcellular location: Mitochondrion matrix
Subcellular location (Human Protein Atlas): Mitochondria
Pathways (Reactome):
Transport of small molecules: Processing of SMDT1
Gene Ontology:
Molecular function: protein binding; ribosome binding
Biological process: calcium import into the mitochondrion; mitochondrial calcium ion homeostasis; protein insertion into mitochondrial membrane; protein insertion into mitochondrial inner membrane from matrix
Cellular component: mitochondrial matrix; mitochondrion; mitochondrial inner membrane
Genetic constraint (gnomAD): Loss-of-function variants: 19 observed, 19.92 expected, observed/expected ratio (o/e) 0.95, 90% interval 0.66 to 1.4. The upper end of that interval is the gene's LOEUF score, 1.4, which puts it in group 5 of 6, group 1 being the genes least tolerant of losing a copy. Missense variants: 243 observed, 264.05 expected, observed/expected ratio (o/e) 0.92, 90% interval 0.83 to 1.02. Synonymous variants: 109 observed, 106.68 expected, observed/expected ratio (o/e) 1.02, 90% interval 0.87 to 1.2.
Homologues: Orthologues: chimpanzee C2orf47 (99% identical), macaque MAIP1 (94% identical), dog MAIP1 (80% identical), mouse Maip1 (77% identical), rat Maip1 (76% identical), pig MAIP1 (76% identical), guinea pig MAIP1 (71% identical), tropical clawed frog maip1 (44% identical), zebrafish maip1 (44% identical), Drosophila melanogaster CG3776 (20% identical), Caenorhabditis elegans Y62E10A.20 (15% identical).
Diseases named in the same sentence as MAIP1 in open-access papers:
MAIP1 is named in the same sentence as 8 diseases in open-access papers, as found by Europe PMC text mining. Sharing a sentence is not in itself a finding about the gene and the disease. The quoted sentences say what the papers report.
diabetes (1 paper, 2024). "The diabetes significant PFKFB3 SNP at the 10p15.1 locus (rs1983890) interacted with MAIP1 and AGAP1 collective SNPs in GGI analysis." (PMID 39313296, 2024). "Pathologic β-cells become long-lived in diabetes despite high energy conservation based on the control over their metabolic state via PFKFB3 and suppression of Ca2+ toxicity via MAIP1." (PMID 39313296, 2024).
esophageal cancer (1 paper, 2022). A primary or metastatic malignant neoplasm involving the esophagus. "Besides, our results also confirmed that MAIP1 may promote the progression of esophageal cancer by reducing tumor immune cell infiltration and blockading immune checkpoint expression levels." (PMID 35747687, 2022).
non-small cell lung carcinoma (1 paper, 2023). A group of at least three distinct histological types of lung cancer, including non-small cell squamous cell carcinoma, adenocarcinoma, and large cell carcinoma. "Parthenolide reduces MCL-1 levels while increasing MAIP-1 levels in non-small cell lung cancer (NSCLC) cells, causing ER stress and inducing cell cycle arrest and apoptosis." (PMID 37047552, 2023).
spastic ataxia 5 (1 paper, 2022). "Research in MAIP1-related disorders (including spastic ataxia 5 and spinocerebellar ataxia) has shown that the proliferation of 293T cell lines was inhibited by high expression of MAIP1." (PMID 35747687, 2022).
tumor (2 papers, 2022 to 2025). "We proposed that MAIP1 overexpression was associated with poor prognosis and tumor immune infiltration in EC." (PMID 35747687, 2022). "In this paper, we describe the identification of MAIP1 as a potential regulator of tumor immune cell infiltration in EC patients and highlight the association of MAIP1 expression with a poorer prognosis in this disease." (PMID 35747687, 2022). "Thus, MAIP1 expression is linked to alcohol history, smoking history, cancer stage, tumor development, and the immune microenvironment of metastasis status." (PMID 35747687, 2022). "At present, there are few MAIP1-related tumor immune infiltration studies in EC, and further investigation is needed." (PMID 35747687, 2022). "Future studies aimed at determining the exact mechanism of MAIP1 in mediating the recruitment of different immune cell populations toward tumor progression or other immune-related processes should be conducted." (PMID 35747687, 2022). "In conclusion, we identified the relationship between MAIP1 expression and the components of the tumor immune microenvironment and immune checkpoints in EC." (PMID 35747687, 2022). "This study aims to determine the clinical significance of MAIP1 in EC and explores its potential molecular mechanisms regulating tumor immune infiltration." (PMID 35747687, 2022). "Accumulating studies suggest that EC-related prognostic gene MAIP1 is involved in immune regulation and the tumor microenvironment, as well as the cancer-promoting mechanism." (PMID 35747687, 2022). "In the TCGA-EC cohort, the overexpression of MAIP1 was observed in tumor tissues compared to normal tissues (p = 0.0038)." (PMID 35747687, 2022). "Moreover, higher MAIP1 expression level also appears to be related to higher tumor stage grade, lymph node migration, and progression of EC." (PMID 35747687, 2022). "The present findings suggested that MAIP1 may act as a tumor-promoting factor regulating the TME and immune mechanisms in EC and may serve as a diagnostic biomarker and a predictor of poor prognosis in EC." (PMID 35747687, 2022).
cancer (1 paper, 2022). A tumor composed of atypical neoplastic, often pleomorphic cells that invade other tissues. "In general, MAIP1 overexpression leads to an immunoreactive microenvironment by recruiting immune cells, and such aberrant infiltration contributes to cancer cell proliferation, distant metastasis, and worsens prognosis." (PMID 35747687, 2022).
MAIP1 also shares sentences with these, for which no sentence is quoted: spinocerebellar ataxia (1 paper); steatosis (1).